NPY (neuropeptide Y)
Diseases named in the same sentence as NPY in open-access papers (continued):
Sharing a sentence is not in itself a finding about the gene and the disease.
neuroblastoma (continued). "In addition to counteracting the toxic effects of Aβ, NPY can also restore neurotrophin levels in neuroblastoma cells." (PMID 34344469, 2021). "Additionally, an antagonist of NPY5R blocked NPY-induced granulosa cell proliferation in EA, as also demonstrated in neuroblastoma and breast cancer cells." (PMID 31915051, 2020). "In SK-N-MC neuroblastoma cells, NPY decreases tyrosine hydroxylase mRNA levels." (PMID 32246073, 2020). "Understanding NPY actions in ES may also have implications for other malignancies rich in NPY and its receptors, such as neuroblastoma and breast cancer, both of which are known to metastasize to bones." (PMID 25714031, 2015). "Neuroblastomas, ganglioneuromas and phaeochromocytomas with significant concentrations of NPY-like immunoreactivity were investigated for different molecular forms of NPY and for significance of proNPY processing." (PMID 10901366, 2000). "The degree of processing of proNPY to NPY in tumour tissue was lower in advanced neuroblastomas with regional or metastatic spread (stage 3 and 4) (n = 6), (41%, 12-100%, median, range), compared to the less aggressive stage 1, 2 and 4S tumours (n = 12), (93%; 69-100%), (P= 0.012)." (PMID 10901366, 2000). "Interestingly, in other cell types, NPY has been shown to stimulate migration of human umbilical endothelial cells, to promote ischemic angiogenesis and vascularization in the rat ischemic hind limb, and to increase motility of neuroblastoma cells." (PMID 35884882, 2022). "NPY also regulated, through the adenylate cyclase/protein kinase A pathway, the ATP-induced increase in internal Ca++ in the human CHP-234 neuroblastoma cell line." (PMID 37373115, 2023). "Already 72 h after transfection, the neuroblastoma cells experienced a marked increase of expression levels of the differentiation markers SCG2 and NPY at mRNA levels." (PMID 33659885, 2021). "In vitro, the DSP toxin OA downregulated NPY content and release of SH-SY5Y neuroblastoma cell line." (PMID 34148100, 2021). "NPY, through Y2R, increased intracellular Ca++ without soliciting Ca++ influx in neuroblastoma cells (LN319), which exclusively express Y2R." (PMID 37373115, 2023). "Moreover, retinoic acid decreased NPY gene expression in neuroblastoma cells (SH-SY5Y) and benefited the proNPY processing to NPY, whereas this acid reduced the expression of YRs in the SK-N-MC neuroepithelioma cell line." (PMID 37373115, 2023). "However, in neuroblastoma cells, Y5R antagonists blocked the pro-survival effect mediated by BDNF (which favors NPY/Y5R expression/NPY release), promoted apoptosis, and sensitized resistant tumor cells to chemotherapy." (PMID 37373115, 2023). "In line with previously published analyses of HOXC9 in neuroblastoma cells, we found a significant up-regulation of genes involved in neuronal differentiation pathways such as DNER, NEFL, DBH, TH, RET, MAP2 and NPY." (PMID 25406647, 2014). "P2X7 receptor-mediated NPY release could be similar to P2X7 receptor-evoked calcium-dependent exocytotic release of ATP observed in the OE and neuroblastoma cells." (PMID 23516531, 2013). "Moreover, NPY, via Y2R, blocked cAMP accumulation mediated by forskolin and omega-conotoxin-sensitive high K+-induced Ca++ influx and attenuated the intracellular release of Ca++ promoted by angiotensin II/bradykinin in human SMS-KAN neuroblastoma cells." (PMID 37373115, 2023). "Thus, the survival NPY/Y5R system is activated by BDNF, and Y5R increases the pro-survival action of this factor and mediates an additional BDNF-independent anti-apoptotic activity contributing to the chemoresistance of neuroblastoma cells." (PMID 37373115, 2023).
Hypertension (38 papers, 2009 to 2025). The presence of chronic increased pressure in the systemic arterial system. "It is also reported that NPY gene polymorphism in CKD patients is associated with the development of hypertension." (PMID 36632461, 2023). "Increased NPY level in the central and/or peripheral nervous system is associated with dyslipidemia, hypertension, obesity, diabetes, and impaired glucose tolerance, all risk factors for atherosclerotic cardiovascular disease." (PMID 34512386, 2021). "In humans and animal models of hypertension, peripheral and central neuropeptide Y is related to the pathological mechanisms underlying hypertension." (PMID 34307371, 2021). "Previous studies reported that NPY is associated with the progression of various cardiovascular diseases, including hypertension, heart failure, and MI." (PMID 31708788, 2019). "Notably, in patients with heart failure and with ST‐elevated myocardial infarction (STEMI), high serum NPY levels are linked to poor coronary microvascular function, arrhythmia, hypertension, impaired recovery of cardiac function and death." (PMID 37460913, 2023). "We conducted the study to test the hypothesis that the reducing effects on hypertension and sympathetic activity caused by EA stimulation may associate with modulating NPY activity within the PVN of hypertensive rats." (PMID 35087687, 2022). "Interestingly, patients with high levels of NPY as defined by the receiver operating characteristic curve were more likely to be hypertensive, and recent data have also implicated NPY in the pathogenesis of hypertension." (PMID 31834357, 2020). "Furthermore, the plasma concentration of NPY has been proved to be a risk factor in cardiovascular system, and increases in various conditions, such as stress, hypertension, and congestive heart failure." (PMID 26131716, 2015). "Various lines of evidence indicate that NPY is involved in the pathological process of hypertension." (PMID 34307371, 2021). "Clinical studies have shown elevated plasma NPY levels in pathological conditions of sympathetic neuropathy, such as hypertension, left ventricular hypertrophy (LVH), myocardial infarction, and heart failure 8,11,12." (PMID 33390770, 2021). "Increased plasma levels of NPY and noradrenaline in patients with hypertension are considered indicators of enhanced sympathetic activity." (PMID 32930881, 2020). "Elevated sympathetic activity at the level of the cardiac post-ganglionic neuron is also observed in the spontaneously hypertensive rat before the onset of hypertension where it also gives rise to elevated NPY levels." (PMID 30283345, 2018). "A mouse model in which NPY is overexpressed in N/E neurones globally has elevated sympathetic activity and is prone to stress-induced hypertension, supporting the idea that NPY contained within N/E-ergic fibers plays a role in sympathetic drive." (PMID 26514659, 2015). "Here, our results suggested that NPY participated in the vascular remodeling during hypertension in pregnancy, but there are still many questions need further researches." (PMID 26131716, 2015). "It has been proved that neuropeptide, especially the peripheral NPY concentration is increased during hypertension in pregnancy." (PMID 26131716, 2015). "The results revealed that NPY concentration and artery open angle were both significantly increased in rats with hypertension in pregnant." (PMID 26131716, 2015). "Our first objective was to map NPY coexpression in central N/E-rgic neurons relevant to hypertension and ADHD, based on three of the most relevant N/E-ergic groups: A6 in the LC, A2 in the NTS, and C1 in the RVLM." (PMID 26514659, 2015). "Neuropeptide Y was reported to bind to receptors and play a role in cardiovascular diseases, including atherosclerotic ischaemia/infarction, arrhythmia, heart failure and hypertension." (PMID 39107876, 2024).
Hypertension (continued). "In CKD patients, the long-term sympathetic hyperactivity as well as hypertension and kidney scarring may stimulate NPY production." (PMID 36632461, 2023). "Alternations of NPY release may play a role in the pathophysiology of at least some forms of hypertension." (PMID 34627325, 2021). "In other words, a high level of NPY in MHO individuals may predict the risk of subsequent metabolic disorders, such as glucose metabolism dysfunction, hyperlipidemia, and hypertension." (PMID 32831640, 2020). "In addition, plasma NPY levels also increased in pathologic conditions of sympathetic neurosis, such as hypertension, left ventricular hypertrophy, MI, and heart failure." (PMID 31708788, 2019). "Furthermore, increased plasma NPY levels are also found in pathological conditions with sympathetic hyperactivity such as hypertension, left-ventricle hypertrophy, and heart failure." (PMID 30283345, 2018). "The results may shed some new lights on the roles of NPY in vascular remodeling occurring in hypertension in pregnancy." (PMID 26131716, 2015). "NPY signalling on the ECs thus appears to be vasodilatory, suggesting that in patients with low NO bioavailability and damaged endothelium, common hallmarks of cardiovascular diseases, circulating NPY could be more vasoactive, contributing to hypertension and reduction in coronary blood flow." (PMID 37460913, 2023). "In addition, in the plasma of patients with hypertension, the level of NPY is elevated." (PMID 34307371, 2021). "In human subjects and animals, plasma NPY levels elevate in response to various stressful conditions, such as cold exposure, tissue injury, particularly accompanied hypoxia, and to sympathetic hyperactivities, such as hypertension and congestive heart and renal failure." (PMID 26131716, 2015). "In summary, our results revealed that the elevated plasma concentration of NPY during hypertension in pregnancy may induce VSMC proliferation mainly via Y5 receptor, which subsequently modulate STAT3 and c-Fos signaling pathways, and then induces vascular remodeling." (PMID 26131716, 2015). "In cultured VSMCs, NPY most effectively stimulated the migration and proliferation of VSMCs at 10-6 mol/L, similar to the plasma concentration in L-NAME hypertension in pregnant rats." (PMID 26131716, 2015). "Neuropeptide Y and oestrogen may represent a biologically plausible interaction between MDD and hypertension, however, this would require investigation." (PMID 31575565, 2019). "mRNA levels of AgRP and NPY in the hypothalamus and brainstem were not affected by any diet and/or hypertension." (PMID 27273815, 2016). "We hypothesized that Neuropeptide Y (NPY), which is a potent mitogenic peptide, participates in modulating proliferation and migration of VSMCs during hypertension in pregnancy." (PMID 26131716, 2015). "It was suggested that alteration in plasma levels of leptin, neuropeptide-Y and α-MSH (melanocyte-stimulating hormone) might be involved in activation of sympathetic activity that leads to hypertension in obese patients." (PMID 22812583, 2012). "Thus, NPY and its receptors might be potential therapeutic targets for the treatment of OSAS-related hypertension in the future." (PMID 34512386, 2021). "Present studies showed that stress-induced hypertension is of complicated pathogenesis which mainly involves the hypothalamus-pituitary-adrenal cortex (HPA) axis, sympathetic nerve-adrenal medulla (SAM) system, renin-angiotensin-aldosterone system (RAS), NO/NOS system, and neuropeptide Y (NPY)." (PMID 26229544, 2015).
prostate carcinoma (34 papers, 2011 to 2026). A carcinoma that arises from epithelial cells of the prostate gland. "Plasma NPY level has been proposed as a biomarker for prostate cancer, and a low NPY expression was associated with aggressive grade, higher genomic risk, and shorter metastases-free survival/progression-free survival in prostate cancer." (PMID 37373115, 2023). "Analyses of clinical prostate cancer samples have also suggested that elevated NPY promotes prostate cancer development and is associated with poor prognosis and therapy resistance." (PMID 36072337, 2022). "Taken together our data demonstrate that ERG-rearrangements in prostate cancer are associated with a variety of transcriptional changes in cancer cells including the expression of metabolic sensors like NPY." (PMID 23390522, 2013). "In contrast, low neuropeptide Y is associated with neuroendocrine development in prostate cancer." (PMID 33572108, 2021). "The findings indicated that NPY-associated mechanisms may be relevant in the progression of prostate cancer at androgen-dependent and -independent stages of the disease." (PMID 25624911, 2015). "In prostate cancer, the decrease of NPY expression is associated with aggressive clinical behavior." (PMID 24289328, 2013). "Average NPY scores were lower in prostate cancers that later recurred (geometric mean 17.6, 95% CI: 9.5-32.5) compared to those that did not (38.7, CI: 23.2-64.4; p: 0.044, d: 0.773)." (PMID 41827933, 2026). "Previous studies have shown that NPY signaling stimulates cancer cell motility and invasive potential in vitro in breast and prostate cancer cell lines, warranting further investigation of the role of NPY1R in PC cell migration." (PMID 40073121, 2025). "Transcripts of prostate cancer-associated biomarkers—kallikrein-related peptidase-2 and -3 (KLK2, KLK3), folate hydrolase 1 (FOLH1), and neuropeptide Y (NPY)—were detected in the platelets of cancer patients but not in those of healthy controls." (PMID 40332071, 2025). "Last, immunohistochemical analysis of human patients with prostate cancer found that NPY, NPY1R, NPY2R, and NPY5R expression was all significantly increased at the invasive border relative to the bulk tumor mass." (PMID 40073121, 2025). "This study evaluated neuropeptide Y (NPY) of the family of endogenous peptides as a new biomarker to diagnose prostate cancer." (PMID 39027656, 2024). "Neuropeptide Y (NPY) and related peptides have been proposed as promising biomarkers for the diagnosis of prostate cancer by previous immunoassays and immunohistochemical studies." (PMID 39027656, 2024). "Compared with PSA, NPY and related peptides (NPYs) were less accurate at diagnosing significant prostate cancer." (PMID 39027656, 2024). "The study was based on immunohistochemical analysis of NPY and its receptors, Y1R, Y2R and Y5R, in tissue samples from benign prostate (BP), primary prostate cancer (PCa) and PCa bone metastases." (PMID 36583743, 2023). "Transcriptional changes in ERG rearrangement-positive prostate cancer cells promoted metabolic changes (e.g., glucose uptake increase) by activating signaling molecules such as NPY." (PMID 37373115, 2023). "The mentioned expressions were upregulated in pre-invasive prostate intraepithelial neoplasia, primary prostate cancer, and metastases, and the presence of the NPY system was increased in the perineural invasion and extraprostatic extension areas." (PMID 37373115, 2023). "A transcriptomic study (17,967 prospective samples) focused on the expression of NPY in prostate cancer development has been performed." (PMID 37373115, 2023). "NPY released from nerve terminals regulates oncogenesis and therapy resistance in prostate cancer: tumor cells favored the increase in NPY-positive nerve fibers, and the inhibition of NPY promoted apoptosis in cancer cells." (PMID 37373115, 2023). "This is because of NPY being highly expressed in prostate cancer cells and being involved in aggressive tumor growth and progression." (PMID 36969009, 2023).
prostate carcinoma (continued). "For example, ERG-rearrangements possibly induce metabolic changes in prostate cancer by increasing glucose uptake through activation of major metabolic signaling molecules such as neuropeptide Y (NPY)." (PMID 37724906, 2023). "This study demonstrated that NF-κB acted as an NPY downstream mediator and that quantifying nerve fibers containing NPY predicted prostate cancer-specific death." (PMID 37373115, 2023). "The data mean that the NPY system is involved from early to disseminated stages in primary prostate cancer development and is involved in cancer perineural spread and invasiveness." (PMID 37373115, 2023). "Animal experiments revealed that NPY released from NE-treated prostate cancer cells promotes macrophage trafficking and IL-6 release, which subsequently activates the STAT3 signaling pathway." (PMID 36072337, 2022). "For example, pro-neuropeptide Y (pro-NPY) was identified as a novel prognostic biomarker in early prostate cancer." (PMID 34638309, 2021). "The activation of β-AR enhanced the secretion of neuropeptide Y (NPY) in a rodent prostate cancer model and subsequently promoted TAM trafficking." (PMID 34869378, 2021). "In well differentiated tumor type the up regulation of VEGFA was identified as a key central node in young prostate cancer patients and down regulation of NPY in old men." (PMID 33575208, 2020). "As NPY is overexpressed in ERG+ prostate cancer cells, these data provide first signs of the fact that ERG rearrangements in prostate cancer possibly modulate metabolic functions through expression of metabolic regulators like NPY." (PMID 23390522, 2013). "When treating prostate cancer cells with NPY, we observed higher glucose uptake in NPY-treated cells." (PMID 23390522, 2013). "Investigations concerning the function of NPY in prostate cancer have been confined to proliferation and migration studies." (PMID 23390522, 2013). "Moreover, NPY was shown to regulate chemotaxis in the highly aggressive LNCaP prostate cancer cell line." (PMID 40073121, 2025). "The plasma NPY level has been suggested as a biomarker for prostate cancer." (PMID 37373115, 2023). "NPY released from nerve terminals regulates therapy resistance and oncogenesis in prostate cancer." (PMID 37373115, 2023). "Moreover, NPY analogs conjugated to gold nanocages have been used as Y1R-targeted agents against tumor cells (PC3 prostate cancer cells)." (PMID 37373115, 2023). "NPY nerve quantification is an independent predictor of prostate cancer-specific mortality." (PMID 37051193, 2023). "NPY has induced diverse signalling pathways and effects in different prostate cancer cell lines." (PMID 35011543, 2022). "For instance, in mouse model of prostate cancer, depression is illuminated to increase the infiltration of myeloid cells and interleukin-6 (IL-6) expressions via mediating sympathetic neuropeptide Y (NPY) signaling pathway and subsequently enhances the tumor growth." (PMID 33411223, 2021). "NPY is a secretary plasma protein mostly over expressed in prostate cancers." (PMID 33575208, 2020). "Pro-neuropeptide Y up-regulation is associated with non-aggressive tumors and regulates proliferation in prostate cancer cell lines." (PMID 26683658, 2015). "We confirmed NPY overexpression in ERG+ prostate cancer cell lines using qPCR and immunoblotting." (PMID 23390522, 2013). "Our data indicate that NPY mediates metabolic functions in prostate cancer cells." (PMID 23390522, 2013). "As NPY is highest expressed in ERG+ prostate cancers it would be interesting to investigate whether ERG+ differ from ERG− prostate cancer bone metastases." (PMID 23390522, 2013). "We measured glucose uptake in vitro to determine whether NPY induces metabolic changes in prostate cancer cells." (PMID 23390522, 2013).